IL6 (interleukin 6)
Diseases named in the same sentence as IL6 in open-access papers (continued):
Sharing a sentence is not in itself a finding about the gene and the disease.
tumor (continued). "In addition, other tumor-promoting cytokines released by CAFs were also inhibited by ANK-SNs, including IL-8, IL-6, and TGF-β (although at levels slightly inferior to ANK)." (PMID 39125655, 2024). "Additionally, catecholamines stimulate the release of pro-inflammatory cytokines, such as interleukin (IL)-6 and IL-8, as well as vascular endothelial growth factor (VEGF), which can enhance angiogenesis and tumor cell dissemination." (PMID 39766169, 2024). "Moreover, their results suggest that JAK2-dependent G6PD phosphorylation is essential for IL-6-induced nucleotide synthesis and thus plays a crucial role in OSCC cell proliferation and tumor growth." (PMID 39796677, 2024). "In the present work, we showed that tumor organoid factors from non-cachectic patients significantly induced IL-8 expression and tended to increase IL-6 expression." (PMID 38339292, 2024). "Within the tumor, markers of immunogenic cell death [calreticulin and high-mobility group box 1 protein (HMGB1)] were increased, and the serum proinflammatory cytokines IL-6, TNFα, and IFNγ also were upregulated, as compared to other treatment groups." (PMID 38803496, 2024). "Hence, we correlated the expression level of the tumor-upregulated gene signature, comprising HAS2, MMP9, CXCL8, CXCL11, IL1B, and IL6, with the ratio of infiltrating M1 macrophages." (PMID 38329386, 2024). "Furthermore, GSEV result spot that tumor promotive signal such KRAS, EMT and IL-6/JAK/STAT3 are restricted under anoikis-related condition." (PMID 39568815, 2024). "Similarly, IL-6, secreted by TAMs and other cells in the TME, acts through various signaling pathways, such as STAT3 and NF-κB, promoting tumor growth, metastasis, and cell survival." (PMID 39766056, 2024). "Conversely, in nonresponsive patients, tumor progression persists, and the immune system remains highly activated, leading to a gradual increase in IL-6 and IL-8 blood levels." (PMID 38774604, 2024). "Thus, 2pHLIP-dMSA induced transient tumor-targeted increases of type I interferon, IFN-β, and the pro-inflammatory cytokines TNF-α and IL-6, indicating activation of the NF-kB and IRF3 signaling pathways, without systemic activation." (PMID 38495104, 2024). "Kinoshita M reported that IL-6 and TGF-β1 secreted by BTC cells promoted the derivation of Tregs and Th17 cells, and Th17 cells accumulated at the tumor margin to accelerate the inflammatory response and promote tumor cell invasion." (PMID 39127853, 2024). "The abnormally activated IL-6/JAK2/STAT3 signaling pathway can contribute to the onset and progression of malignant tumors by affecting the proliferation, migration, invasion, angiogenesis, and apoptosis of tumor cells." (PMID 38881895, 2024). "Then, bone marrow derived MDSCs (BM-MDSCs) were generated and activated using GM-CSF plus IL-6 with or without LLC tumor explant supernatants." (PMID 38402237, 2024). "It is crucial to note that therapy-induced tumor cell death promotes the production of growth factors and cytokines, including WNT, EGF, TNF, IL-17, and IL-6, by cells in the TME to promote the survival of remaining tumor cells and play a role in fostering therapy resistance." (PMID 38799159, 2024). "It exhibits anti-inflammatory properties by reducing cytokines, such as IL-6 and TNF-α, which may inhibit tumor growth." (PMID 39766169, 2024). "Anti-IL-6 pathway therapy was utilized as early as 1995 to treat or reverse constitutional toxicity in murine models, without an effect on tumor growth per se." (PMID 38689325, 2024). "In addition to the tumor invasive role, enrichment analysis revealed the overexpressed ELF4 was involved in the immune regulation, characterized by the elevated activity of Il6/Jak/Stat3 signaling, interferon alpha (IFN-α) response, and IL2/Stat5 signaling." (PMID 39132148, 2024).
tumor (continued). "Copper not only regulates the release of angiogenic factors like fibroblast growth factor (FGF) and inflammatory cytokine IL-1α, but also promote tumor angiogenesis and metastasis by directly activating various proangiogenic molecules, including VEGF, SOD1, FGF2, TNF-α, and IL-6." (PMID 39691393, 2024). "In addition, cancer-associated adipocytes have been found to release high levels of cytokines and growth factors such as IL-6, CCL2, CCL5, IL1β, TNFα, and VEGF, which collectively contribute to enhanced tumor cell proliferation, invasion, and angiogenesis." (PMID 38800384, 2024). "Vaccination with ME49Δompdc resulted in an elevated expression of positive genes, including Ifng, Tnfa, and Il12, while suppressing negative genes like Il6, Pd1, and Pdl1, in tumor or splenocytes compared to cells from tumor‐bearing mice treated with the PBS." (PMID 39031880, 2024). "In addition, MMP-9 produced by tumor cells drives malignant progression and metastasis and high levels of inflammatory cytokines such as TNF-α, IL-1β, Il-6, and IL-8 present in CM can also significantly increase MMP-9 expression." (PMID 39072314, 2024). "In this study, we aimed to determine the predictive value of pre-RT IL-6 concentration on the prognosis after RT of patients with confined HCC without tumor thrombus." (PMID 39619013, 2024). "The enriched pathways in the hA-MSCs provided evidence for increased cell migration, which can be partially attributed to the intrinsic homing property and recruitment of hA-MSCs to the tumor site mediated by released inflammatory cytokines such as IL6 and TNF-α from tumor cells." (PMID 38333871, 2024). "Current research suggests that macrophages may promote EMT through signaling pathways such as IL-35/JAK2-STAT6-GATA3, IL6/Jak/Stat3/THBS1, or STAT3/miR-506-3p/FoxQ1, which facilitate the invasion, and metastasis of tumor cells." (PMID 39068459, 2024). "Notably, a significant rapid rise in tumor- and metastases-promoting molecules such as matrix metalloproteinase-9 (MMP-9), interleukin-6 (IL-6), hepatocyte growth factor (HGF), and placental growth factor (PLGF) was observed immediately (2 h) after surgery." (PMID 39451257, 2024). "This is in good agreement with the results of this work, where animals from the “LLC_Gr_HCA” group showed a decrease in the IL-6 levels and an increase in the percentage of animals with undetectable LIF levels, along with a decrease in the tumor size and metastasis." (PMID 38891915, 2024). "In the present study, we found increased inflammation, lymphangiogenesis, M2-TAM, and CAFs in tumor tissues composed of cancer cells that originally promoted EMT induction, and CCL5 and IL-6 secreted by the inflammation further enhanced EMT induction in cancer cells." (PMID 39126553, 2024). "Furthermore, it has been observed that insulin-resistant tumor tissues exhibit enhanced inflammatory responses and increased secretion of inflammatory factors, such as TNF-α and interleukin-6 (IL-6)." (PMID 38449844, 2024). "Additionally, CAFs secrete growth factors like TGF-β, IL-6, and hepatocyte growth factor (HGF), which promote tumor proliferation and angiogenesis." (PMID 39200315, 2024). "However, the presence of pro-inflammatory cytokines such ad IL-17, IL-6, IL-1β, and TNF-α leads to the chronic activation of inflammatory signals that not only suppresses adaptive immune responses, but also induce tumor growth." (PMID 39767682, 2024). "In addition, SIX4, STAT3, IL-6, SOX2, and C-JUN were upregulated in tumor spheres compared to adherent cells." (PMID 39309424, 2024). "However, utilizing FACS-sorting and EGC-specific genetic IL-6 and IL-1R depletion models, we confirmed the critical role of IL-1-triggered EGC-IL-6 release as a regulator of tumor growth and SPP1+ TAM differentiation." (PMID 39030280, 2024).
tumor (continued). "The presence of biofilms promotes inflammatory interleukin 6 (IL-6) activity and signal transducer and activator of transcription (STAT) signaling, which supports tumor proliferation and carcinogenesis and damages tight junctions, allowing for tumor invasion and metastasis." (PMID 38672096, 2024). "Moreover, our study found significantly elevated levels of the chemokine CCL17 (TARC) and the cytokine IL-6 in cHL patients at DIA, both of which are known to play crucial roles in modulating the tumor microenvironment." (PMID 39769007, 2024). "Similarly, IL-6 signaling can activate STAT3, which in turn can regulate miRNAs targeting PTEN, further diminishing its tumor-suppressive effects." (PMID 39298504, 2024). "Notably, researches have demonstrated that activation of IL-6/IL-6R up-regulates VEGF, thereby promoting tumor angiogenesis 33,34." (PMID 39247606, 2024). "Mechanistic investigation demonstrated that FXR specifically bound to the promoters of IL-6ST and IL-6 genes to upregulate their transcription, thereby leading to activation of the Jak2/STAT3 signaling pathway, which facilitated tumor migration, invasion, and angiogenesis in NSCLC." (PMID 38360812, 2024). "Furthermore, the interaction between the IL‐6/STAT3 pathway and the nuclear receptor PXR can synergistically modulate changes in the tumour microenvironment and mitigate resistance mechanisms." (PMID 39495702, 2024). "Importantly, circNOX4 fuels tumor growth and metastasis by activating the fibroblast niche via the miR-329-5p/FAP/IL-6 axis." (PMID 38459511, 2024). "Low levels of IL6 and CRP may indicate a less inflammatory tumor microenvironment, which can enhance the effectiveness of treatment with ICIs." (PMID 38952546, 2024). "IL‐6, a cytokine whose blockade was discovered to abrogate immunotherapy toxicity and promote tumor immunity, was unsurprisingly higher in the plasma of non‐responders." (PMID 39467150, 2024). "Further analysis revealed that IL-6 level was significantly higher in the non-tumor group of patients who were positive for Vpr (P = 0.0283), but not in the tumor group (P = 0.680)." (PMID 38166062, 2024). "In contrast, there was no noticeable change in tumor burden between TC-1 tumor-bearing mice treated with isotype or αIL6, suggesting that blockade of IL6 has the potential to limit development and progression of HPV − HNSCC." (PMID 38468260, 2024). "Specifically, as compared to WT animals, A10-PPARα mice have more macrophages within the tumor and these intratumor (IT) macrophages expressed increased levels of cytokines such as tumor necrosis factor α (TNF-α), interleukin-6 (IL-6), IL-12/IL-23p40, and inducible nitric oxide synthase (iNOS)." (PMID 38746124, 2024). "In addition, the serum and tumor homogenate concentrations of proinflammatory cytokines, including IFN‐γ, TNF‐α, IL‐6 and IL‐1β, increased significantly in the B16F10 cell–rechallenged mice of the HM‐NPs group." (PMID 38353384, 2024). "For instance, PD-L1 expression is induced in tumor cells by IFN-γ/STAT-1 and IL-6/STAT3 signaling." (PMID 39596207, 2024). "The transcriptome profile of HGSOC tumors from the TCGA data portal revealed that an increase in IL-6 expression was strongly related to poor tumor-free survival and played a key role in CSC self-renewal and maintenance, treatment resistance, and tumor invasion." (PMID 38575576, 2024). "Collectively, we found that ANK-SNs did not have cytotoxic effects, were efficiently internalized through specific interaction at the cell surface with IL-1R1, and down-modulated the secretion by CAFs of TSLP, IL-8, IL-6, and TGF-β, thus dampening their tumor-promoting functions." (PMID 39125655, 2024). "Tumor cells promote CAF generation, and the CAFs, in turn, improve the invasiveness and metastasis of the malignant T cells through the IL-6/JAK2/STAT3/SOX4 or IL-6/HIF-1α/SOX4 pathway." (PMID 39963655, 2024).
tumor (continued). "The IL-6/STAT3 signaling pathway may play an essential role in the TIME; IL-6-mediated STAT3 activation in the TME inhibits the functional maturation of DCs, thus activating effector T cells and blocking the emergence of anti-tumor immunity in cancers." (PMID 38361933, 2024). "In particular, IL-6, an inflammatory cytokine, and vascular endothelial growth factor (VEGF) secreted by tumor cells have been shown to stimulate megakaryocyte differentiation and promote tumor growth." (PMID 39596977, 2024). "It was reported that IL-6 trans-signaling is required to promote the development of HCC by preventing DNA-damage-induced hepatocyte apoptosis and inducing endothelial cell proliferation, which in turn promotes tumor angiogenesis." (PMID 39071840, 2024). "Activated B cells are known to secrete inflammatory cytokines such as IL-6, Il-1α, TNF-α and Il-1β itself, which may stimulate IL-β secretion and NfκB activation in tumor cells." (PMID 39801513, 2024). "The hyper-activation of the IL-6/JAK/STAT3 cascade plays a bi-directional role in tumor progression and the related therapeutic strategies to target this pathway failed in a panel of tumor types." (PMID 38274367, 2024). "Two studies reported a better prognosis for CC patients with lower IL-6 expression, but these studies analyzed IL-6 expression in tumor tissue but not in serum." (PMID 38541074, 2024). "Epigenetic modulations, including modification in DNA components and histones, telomer disruptions, expression of oncogenic and tumor suppressive microRNA (miR/miRNA), and non-long coding RNA, affect the regulation of IL6, IL6R, and its signaling." (PMID 39766086, 2024). "We also found that circUBA2 could upregulate STC1 expression via miR-144-5p sponging and further activates the IL-6/JAK2/STAT3 signaling pathway, thereby promoting stemness and tumour progression in GC in vivo and in vitro." (PMID 39103836, 2024). "At the same time, STAT3 upregulates the expression of lncRNAs by binding to their promoters, forming lncRNA/IL-6/STAT3 or lncRNA/IL-11/STAT3 loops, which enhance the drug resistance of tumor cells, or promoting tumor growth and metastasis in vivo and inhibiting tumor cell apoptosis." (PMID 38172648, 2024). "Comparing non-sarcomatoid to sarcomatoid samples, bivariate Moran’s I did not identify any ligand-receptor pairs from either EMT or IL6/JAK/STAT3 gene sets that were spatially correlated in either the tumor or stroma FOV." (PMID 39639369, 2024). "Nevertheless, the association between the upregulation of cytokines TGF-β, IL-4/IL-13, IL-10, IL-6, and IL-2 and the overexpression of FAP across multiple tumor types highlights a crucial link between FAP+ CAFs, tumor progression, and evasion of immune surveillance." (PMID 39035007, 2024). "Of note, pharmaceutical inhibition of FXR significantly suppresses IL-6/IL-6ST/p-STAT3 signaling and reduces metastatic tumor burden in mouse NSCLC metastasis models, suggesting a potential therapeutic approach for this subgroup (characterized by FXRhigh) of metastatic NSCLC patients." (PMID 38360812, 2024). "We found that the increased number of Ly6Clow macrophages in CD244fl/flLysMcre mice was accompanied by a significant upregulation of anti-tumorigenic macrophage markers and cytokines, including CD80, NOS2, IL6, and IFNB1, in CD11b+ sorted tumor-infiltrating macrophage populations." (PMID 38424542, 2024). "TAMs also secrete IL-6 and promote STAT signaling resulting in tumour growth and progression." (PMID 38384463, 2024). "The authors’ research further indicates that inhibiting key factors of the MAPK pathway, such as MEK, can increase the immunogenicity of tumor cells leading to the upregulation of MHC-I (major histocompatibility complex class-I) expression and increased mRNA levels of IFN-γ, IL-6, IL-1B, and TNF-α." (PMID 38426097, 2024).
tumor (continued). "Extracellular vesicles overexpressing esophageal cancer related gene-4 significantly inhibit the expression of inflammatory cytokines (IL-1β, IL-6, IL-8) and activate the p38–AMPK signaling pathway to suppress the inflammatory response and induce anti-tumor effects in vitro and in vivo." (PMID 38890722, 2024). "IL-6 is a pleotropic cytokine that is frequently expressed at high levels in various tumor tissues and non-malignant tissues in response to tissue damage and infections." (PMID 38482486, 2024). "Tumor-associated cytotoxic T cells (CD8+GranzymeB+) cells were not different compared with IL6-low and -high tumors; however, in IL6-high tumor Tregs trended up, and macrophages were significantly enriched." (PMID 38451784, 2024). "Additionally, pro-inflammatory cytokines, including IL-6 within the PDAC tumor microenvironment (TME), are known to facilitate the evasion of anti-tumor immune responses and contribute to chemotherapy resistance." (PMID 38672257, 2024). "In particular, IL-6 mRNA levels in subcutaneous tumors were inconsistent with their expression levels in tumor cells, indicating that IL-6 expression in vivo is not dependent on cancer cells." (PMID 38274367, 2024). "In this sub-cohort with comparable tumor stages, IL-6 was no longer found to be significantly different." (PMID 38383695, 2024). "To finally investigate the effect of EGC-derived IL-6 on the SPP1+ TAM differentiation and tumor development in vivo, we orthotopically injected MC38 cells in the colonic mucosa of mice with a glial-specific deletion of IL-6 (SOX10CreERT2IL-6fl/fl) and their littermates (SOX10CreERT2IL-6wt/wt)." (PMID 39030280, 2024). "In addition, IL-6/JAK/STAT3 signal transduction upregulates immune checkpoint ligand PD-L1 expressed and regulates MDSCs to suppress tumor immunity." (PMID 39372416, 2024). "Moreover, we examined the roles of several growth factors and inflammatory cytokines in PDL1 expression HNSCC cells, such as epidermal growth factor (EGF), LPS, IL-6, IL-1β, and TNF-α, commonly in tumor microenvironment." (PMID 38945975, 2024). "Plasma IL-6 and GDF-15 were both increased at around two weeks following tumor inoculation." (PMID 38824130, 2024). "Activated dendritic cells stimulate the formation of M2 macrophages to secret some cytokines, such as IL-6, CXCL8, VEGF, and TGF-β, which could suppress the adaptive immune response and promote tumor growth." (PMID 39060620, 2024). "In addition, higher expressions of IL‐6, TNF‐α, and IFN‐γ were expressed in lung metastatic nodes of the RBC‐PEI‐AD11 group compared with other groups to promote anti‐tumor immune response." (PMID 37997186, 2024). "In addition, the ELISA assay was used to measure the concentrations of IL-6 and TNF-α, which are critical in the regulation of the inflammatory response in the tumor microenvironment." (PMID 38926454, 2024). "In the anti-tumor activity test, D-mannitol is considered to enhance the phagocytosis of mouse macrophages and promote the release of immune active substances’ tumor necrosis factor-α (TNF-α) and interleukin-6 (IL-6) and improve the immune function of mice." (PMID 38786711, 2024). "Conversely, in the presence of high levels of IL-6 and PGE2, intratumoral cDC2s can also be driven toward a pro-tumor phenotype characterized by CD14 expression, upregulation of markers usually associated with tumor-associated macrophages (TAMs), and impaired antigen processing and presentation." (PMID 38903502, 2024). "In this study, we report that mEHT monotherapy stimulated interleukin‐1 beta (IL‐1β) and interleukin‐6 (IL‐6) expression, and consequently cyclooxygenase 2 (COX‐2), which may favor a cancer‐promoting tumor microenvironment." (PMID 38217262, 2024). "Although this result was interesting, bulk RNA sequencing did not permit analysis of IL6 with respect to different tumour compartments." (PMID 39766336, 2024).